FOXP3 (forkhead box P3)
Diseases named in the same sentence as FOXP3 in open-access papers (continued):
Sharing a sentence is not in itself a finding about the gene and the disease.
esophageal cancer (38 papers, 2013 to 2025). A primary or metastatic malignant neoplasm involving the esophagus. "Previous studies have also reported that tumor-infiltrating FoxP3+ regulatory T cells (Tregs) are associated with favorable prognosis in colorectal, head and neck, and esophageal cancers." (PMID 41184982, 2025). "In contrast, FoxP3+ Tregs are associated with improved survival in colorectal and esophageal cancer." (PMID 31639056, 2019). "MiR-149-3p prevented regulatory T-cell differentiation and immune escape via posttranscriptional inhibition of FOXP3 mRNA in esophageal cancer." (PMID 36593242, 2023). "Immunohistochemical staining of the Treg cell marker FoxP3 following neoadjuvant radiochemotherapy for esophageal cancer has been reported as a prognostic marker for cancer-specific survival." (PMID 34269847, 2022). "In the case of esophageal cancer, high numbers of FOXP3+ cells was reported to be an indicator of poor as well as good prognosis." (PMID 32884895, 2020). "Overall, 140 cases of esophageal cancer underwent an immunohistochemical analysis of the PD-L1 expression and its association with the expression of the α smooth muscle actin, fibroblast activation protein, CD8, and forkhead box P3 (FoxP3) positive cells." (PMID 37668710, 2023). "We have previously shown that FoxP3 is a favorable prognostic marker for esophageal cancer." (PMID 34203319, 2021). "In addition, analysis of Treg frequency and FOXP3 mRNA level in patients with esophageal cancer showed a decrease of both factors after chemotherapy, suggesting that FoxP3 inhibition can be an effective strategy in cancer therapy." (PMID 29785404, 2018). "Moreover, using IHC, we also detected a high density of intratumoral FoxP3+ Tregs in PDAs, similar to results observed in other malignancies, including breast, ovarian, gastric and esophageal cancers." (PMID 24637664, 2014). "For example, CAFs increase the ratio of FoxP3+ (Tregs) and CD8+ tumor-infiltrating lymphocytes via IL-6 in TME, and IL-6 blockade enhances the immunotherapy efficacy in esophageal cancer models." (PMID 36703971, 2022). "Another study found that a high CD8+/CD4+ ratio and a low FOXP3/CD8 ratio correlate with prolonged survival of PD-L1+ patients but not for that of PD-L1− patients with esophageal cancer." (PMID 34797860, 2021). "Furthermore, a high CD8+/CD4 + ratio and low FOXP3/CD8 ratio correlate to longer survival of stromal PD-L1 + patients, but not that of stromal PD-L1 − patients with esophageal cancer." (PMID 38233811, 2024).
endometriosis (36 papers, 2010 to 2025). The growth of functional endometrial tissue in anatomic sites outside the uterine body. "Previous studies only found an association of Foxp3 expression in the endometrium of patients with mild endometriosis in the peri-implantation period." (PMID 38781760, 2024). "The cumulative effect of interaction of FCRL3 –169T>C and FOXP3 –2383C>T polymorphisms has previously been demonstrated in the development of endometriosis." (PMID 30021560, 2018). "(Firmicutes phylum) observed in P-EOSIS may play a role in endometriosis associated inflammation by induction of colonic Foxp3+ regulatory T cells and activation of T cell dependent immunoglobulin A production." (PMID 34914785, 2021). "Furthermore, the combination of FCRL3 and FOXP3 genotypes increases the risk of endometriosis, as observed in the Brazilian population samples." (PMID 32802844, 2020). "Foxp3+CD39+CD73+ Treg cells are decreased in the blood of women with deep infiltrating endometriosis but increased in the peritoneum and endometriotic lesions." (PMID 40508002, 2025). "In a case-control study including 55 endometriosis patients, increased FOXP3 + Treg in lesions showed a positive correlation with chronic pelvic pain." (PMID 40679648, 2025). "One study found that women with advanced endometriosis had significantly higher percentages of CD25+FOXP3+ Treg cells in peritoneal fluid compared to those with early endometriosis and control subjects." (PMID 40725782, 2025). "An imbalance of Tregs (CD4 + CD25 + FOXP3+) contributes to the immune-suppressive microenvironment in endometriosis, promoting the establishment and maintenance of ectopic lesions." (PMID 40679648, 2025). "This study has demonstrated a notable decrease in the levels of Treg Foxp3+CD3+CD4+CD25HighCD39+CD73+ cells in the peripheral blood of women with endometriosis compared to healthy controls." (PMID 38781760, 2024). "Overall, within the eutopic endometrium the fold induction of RORγt transcripts were significantly higher than the Foxp3 transcripts following the induction of endometriosis; thus, driving an inflammatory profile in the eutopic endometrium." (PMID 35102185, 2022). "The proportion of immune cells, including macrophages, NK cells, and CD4+Foxp3+ regulatory T cells (Tregs), is increased in the peritoneal fluid of women with endometriosis." (PMID 36310658, 2022). "Endometrial FOXP3 in women with endometriosis decreases linearly from the early to late proliferative phase." (PMID 35563743, 2022). "The prevalence of FOXP3+ Tregs in an endometriotic environment during secretory phase prevent leukocyte recruitment to the sites of endometriosis." (PMID 33800594, 2021). "Treg cells and increased FOXP3 expression were reported in the eutopic and ectopic endometrium in women with endometriosis." (PMID 34501240, 2021). "In this study, women with endometriosis were more likely to have a decreased percentage of CD25 (high) FOXP3+ Treg cells in the peripheral blood than women in the control group." (PMID 34829767, 2021). "Though limited in evidence, FOXP3 also plays a role in the inflammatory aspect of endometriosis, which correlates with miR-155-5p being a promoter of inflammation." (PMID 33800594, 2021). "Although some studies demonstrated increased levelsof CD4+CD25+FoxP3+ cells in the PF andectopic tissue of endometriosis subjects, we did notdetect this increase in our study." (PMID 33098386, 2020). "As literature data indicate that Treg dysfunction plays an important role in the development of endometriosis, we compared their relative FoxP3 expression in NE-PBMC, E-PBMC, and E-PTL cohorts." (PMID 32231038, 2020). "These researchersintroduced CD4+CD25+FoxP3+ cells as Tregs andreported similar numbers of Treg cells between mild andadvanced endometriosis." (PMID 33098386, 2020). "Like other researchers, this groupintroduced CD4+CD25+FoxP3+ as Tregs and reportedsimilar numbers of blood Tregs in endometriosis andcontrol samples." (PMID 33098386, 2020).
endometriosis (continued). "The percentage of CD25+FOXP3+Treg cells is significantly increased in the peritoneal fluid of women with endometriosis." (PMID 32802844, 2020). "FoxP3 mRNA is increased in ectopic endothelial tissue and the percentage of Tregs is significantly decreased in the peripheral blood of women with endometriosis, compared to healthy controls." (PMID 28902871, 2017). "Foxp3+ regulatory T (Treg) cells contribute to the local dysfunctional immune environment in endometriosis, an estrogen-dependent gynecological disease, which affects the function of ectopic endometrial tissue clearance by the immune system." (PMID 27906184, 2016). "The proportion of CD4+Foxp3+ regulatory T cells (Tregs) is significantly increased in the peritoneal fluid of women with endometriosis." (PMID 25275597, 2014). "The percentage of CD4+Foxp3+ Tregs in the peritoneal fluid from women with endometriosis was furthermore highest at stage III–IV." (PMID 25275597, 2014). "Human MUC1 TG mice have since been crossed with conditional-endometriosis transgenic mice, showing the presence of regulatory Foxp3+ T cells and antibodies against MUC1 during endometriosis, with potential implications for cancer progression." (PMID 23509794, 2013). "Some clinical research found that FOXP3 + Treg cells were increased in lesions, decreased both in peripheral blood and peritoneal fluid, and increased in eutopic endometrium during the follicular phase in endometriosis patients." (PMID 40679648, 2025). "Research on the three FoxP3 + cell fractions in endometriosis is limited." (PMID 40679648, 2025). "The results showed a significant increase in the expression of protein C7 and the number of CD3+FOXP3+ Treg cells in endometriosis lesions compared to normal endometrium (protein C7 expression, NE groups vs. OEMs groups, p < 0.001; CD3+FOXP3+ Treg cell number, NE groups vs. OEMs groups, p < 0.001)." (PMID 38424274, 2024). "The observed decrease in Foxp3+CD39+CD73+ Treg cells in the peripheral blood of endometriosis patients may have profound implications for the pathophysiology of the disease." (PMID 38781760, 2024). "A characteristic of regulatory T cells, FOXP3 is responsible for the immunosuppressive capacity of multipotent stromal cells and may participate in regulating immune responses in endometriosis." (PMID 35563743, 2022). "Additionally, in ovarian endometriotic lesions, we observed significantly higher numbers of FOXP3+ T cells than in the normal endometrium or in the eutopic endometrium of the endometriosis patients." (PMID 35260161, 2022). "There are suggestions in the literature that in endometriosis, increased FoxP3 Treg response may lead to cancer progression." (PMID 34900746, 2021). "In endometriosis, increased FoxP3 Treg response is suggested to lead to cancer progression." (PMID 34900746, 2021). "Additionally, peritoneal fluid (PF) from women with endometriosis has a higher concentration of FOXP3-expressing TCD4+CD25high cells than the PF of control patients." (PMID 33800594, 2021). "Methylation of the FOXP3 promoter could be partly responsible for pain that women with endometriosis may experience based on the trend of increased methylation in cells treated with PF from endo patients, particularly those reporting pain." (PMID 33800594, 2021). "In addition to Sampson’s theory of retrograde menstruation, endometriosis pathogenesis is facilitated by a privileged inflammatory microenvironment, with T regulatory FoxP3+ expressing T cells (Tregs) being a significant factor." (PMID 28902871, 2017). "Interestingly, in humans, the expression of the transcription factor forkhead P3 (Foxp3), a distinctive surface marker for Treg cells, is upregulated in the endometrium of women with endometriosis." (PMID 27740937, 2017).
endometriosis (continued). "Considering that endometriosis is an estrogen-dependent disease, and that estrogen enhances Foxp3 expression and Treg cell function, we explored whether estrogen regulates the differentiation of Treg cells in endometriosis." (PMID 27906184, 2016). "The concentration of transforming growth factor-β (TGF-β), another key cytokine involved in CD4+Foxp3+ Treg function, was lowest in the peritoneal fluid from healthy controls, elevated in women with early stage endometriosis and highest in women with advanced stages of endometriosis." (PMID 25275597, 2014). "Quantitative analysis showed that the percentage of CD4+Foxp3+ Tregs was significantly increased not only in the total mononuclear cells but also in CD4+ T cells of peritoneal fluid from women with endometriosis (stage I–II and stage III–IV) compared with healthy fertile women." (PMID 25275597, 2014). "A more recent study by the same group adds the hypothesis that FoxP3 and FCRL3 polymorphisms may have a cumulative effect in increasing the risk of developing endometriosis." (PMID 23843796, 2013). "The percentage of FOXP3+ cells within the subpopulation of CD4+ lymphocytes was statistically significantly higher in the tissue samples from the patients with endometriosis as compared with the percentage found in the tissue samples from the patients who had developed ectopic pregnancies." (PMID 20923543, 2010). "CD25+CD4+FOXP3+ T cells were found in all the examined endometriosis tissue samples." (PMID 20923543, 2010). "Moreover, several studies have demonstrated that during inflammation (e.g., endometriosis-related), Treg cells may lose their phenotypic properties and be converted into effector T cells secondary to the alteration of Foxp3 expression and stability." (PMID 35935991, 2022). "Additionally, there was an increase in miR-155/FoxP3 expression which may be working in coordination with the PRC2 complex to drive the progression of endometriosis." (PMID 34900746, 2021). "In Papio anubis, induction of endometriosis alters the peripheral and endometrial populations of Tregs, whereas in humans, several studies have shown that Tregs are present in eutopic and ectopic endometrial tissues and that FOXP3 mRNA levels are elevated in human endometriotic lesions." (PMID 29391020, 2018). "To determine if induction of endometriosis altered peripheral immune cell populations, we identified nTregs (CD4+CD25+Foxp3+), iTregs (CD4+CD25−Foxp3+) and Th17 cell populations in blood samples collected over time." (PMID 35102185, 2022). "This study explored the role of miR-155 in endometriosis by studying its interactions with the PRC2 complex, JARID2 and FOXP3." (PMID 33800594, 2021). "Given the importance of FoxP3 in the pathogenesis of endometriosis, we aimed to confirm a potential PIF interaction with FoxP3 signaling." (PMID 28902871, 2017). "In line with a role for a modified immunity in the pathogenesis of endometriosis, CD4+/FoxP3+ Tregs are present in endometriotic lesions." (PMID 28902871, 2017). "Importantly, within endometriosis lesions, the expression of protein C7 was positively correlated with the number of CD3+FOXP3+ Treg cells (Spearman: 0.9, p = 0.037)." (PMID 38424274, 2024). "One study found that endometriotic lesions in the deep rectosigmoid colon express higher levels of Foxp3 compared to other types of endometriosis or in individuals without endometriosis." (PMID 37632165, 2023). "A higher percentage of FoxP3 Tregs, and immunosuppressive cytokines, interleukin-10 (IL-10), transforming growth factor beta (TGF-β) levels are present in the PF and increased expression in endometriotic tissue of patients with endometriosis compared to control women." (PMID 34900746, 2021).
endometriosis (continued). "For example, one case-control study including 17 histopathologically-confirmed ovarian endometriosis patients and 15 women without endometriosis compared the percentage of CD25 (high) FOXP3+ Treg cells in the peripheral blood and peritoneal fluid between the groups." (PMID 34829767, 2021). "Therefore, we analyzed the relative abundance of Treg (CD4+/FOXP3+) cells in the PF of women with and without endometriosis." (PMID 32572831, 2020). "Additionally, higher expression of FoxP3 mRNA has been detected in the endometrium of infertile, advanced stage endometriosis women; that said, the Foxp3 protein was not significantly higher in these patients compared to fertile controls." (PMID 27740937, 2017). "Here, using eutopic and ectopic tissues, as well as peritoneal fluid (PF) from IRB-approved and consented patients with and without endometriosis, the expression of PRC2 complex components, JARID2, miR-155 (known regulators of EZH2), and a key inflammatory modulator, FOXP3, was measured." (PMID 33800594, 2021).
experimental autoimmune encephalomyelitis (36 papers, 2008 to 2025). An autoimmune demyelinating disease of the central nervous system that is produced experimentally in animals by the injection of homogenized brain or spinal cord in Freund's adjuvant. "Deletion of Ctps1 in T cells or treatment with a CTPS1 inhibitor rescued Foxp3-deficient mice from fatal systemic autoimmunity and reduced the severity of experimental autoimmune encephalomyelitis." (PMID 38438357, 2024). "This shift in cytokine profiles promotes the generation of antigen-specific Foxp3+ regulatory T cells (Tregs) and type 1 regulatory T (Tr1) cells, thereby combating inflammation in experimental autoimmune encephalomyelitis (EAE) mouse models." (PMID 39956891, 2025). "In vivo or in vitro exposure to 17β-estradiol increases CD4+CD25+ T cell numbers and FoxP3 expression in Experimental Autoimmune Encephalomyelitis (EAE)." (PMID 33746959, 2021). "FOXP3+ Tregs mediate disease resistance and recovery from experimental autoimmune encephalomyelitis (EAE), an animal model of MS." (PMID 32522287, 2020). "The Bluestone group, using Foxp3-Cre reporter mice in an Experimental autoimmune encephalomyelitis (EAE) model observed that some of the Treg cells downregulated Foxp3 expression and these were referred to as exFoxp3 cells." (PMID 30941142, 2019). "Adoptive transfer of blastogenic CD25high FOXP3+ Tregs from MOG35-55-specific 2D2 TCR transgenic mice suppressed experimental autoimmune encephalomyelitis in pretreatment and therapeutic protocols." (PMID 29312311, 2017). "Injection of CTlo- or cAMP-DCs exerted MOG peptide-specific protective effects in experimental autoimmune encephalomyelitis (EAE) by inducing Foxp3+ Tregs and reducing Th17 responses." (PMID 28759565, 2017). "A murine experimental autoimmune encephalomyelitis (EAE) model was used to test the stability of Foxp3+ iTreg cells." (PMID 28729608, 2017). "We suggest that the P3 Treg phenotype is analogous to a recently described ex-FOXP3 Treg subset identified in experimental autoimmune encephalomyelitis." (PMID 25092890, 2014). "SnL are also upregulated on subsets of CD4+FoxP3+ regulatory T cells (Tregs) in experimental autoimmune encephalomyelitis (EAE), leading to an Sn-dependent reduction in numbers of Tregs and exacerbation of disease." (PMID 24286366, 2013). "In this study, it is described how the synthetic peptide dNP2‐ctCTLA‐4 can induce Foxp3+ Tregs in mice and human peripheral blood mononuclear cells (PBMCs), ameliorate experimental autoimmune encephalomyelitis (EAE) progression with long‐term regulation and prevent disease relapse." (PMID 34306974, 2021). "Additionally, rapamycin enriched antigen-specific Foxp3+ Treg cells to promote organ transplant tolerance and inhibited relapsing experimental autoimmune encephalomyelitis (EAE) by modulation of both effector/regulatory T cells." (PMID 24432019, 2014). "In a previous study on JM4 in experimental autoimmune encephalomyelitis, we demonstrated that this treatment blocked dendritic cell proliferation and this was associated with a decrease in Th17 cells, proinflammatory cytokines, and increase in CD4 FoxP3 Treg cells." (PMID 31572168, 2019). "To induce this identity in proinflammatory CD4+ Teff cells from mice with experimental autoimmune encephalomyelitis (EAE), we first optimized conditions for efficient Foxp3 induction." (PMID 40762956, 2025). "In experimental autoimmune encephalomyelitis and chronic inflammation in enteritis, the expression of AIM2 by Tregs maintains the expression of the transcription factor forkhead box P3 (FOXP3)." (PMID 37046775, 2023). "The lysine motif of ctCTLA‐4, not tyrosine motif, is required for Foxp3 expression for Treg induction and amelioration of experimental autoimmune encephalomyelitis (EAE)." (PMID 34306974, 2021).